TRPA1 (transient receptor potential cation channel subfamily A member 1)
Diseases named in the same sentence as TRPA1 in open-access papers (continued):
Sharing a sentence is not in itself a finding about the gene and the disease.
psoriasis (continued). "In aggregate, these results suggest that neutrophils recruitment (a prominent feature of human psoriasis and many murine models of psoriasis) is, in part, regulated by TRPA1 through modulation of expression of neutrophil chemoattractants such as CXCL1 and CXCL2." (PMID 31111624, 2019). "Finally, these studies imply that it is a relevant target for pharmacologic intervention in psoriasis and that further study is needed to elucidate the role of TRPA1 in psoriasis." (PMID 31111624, 2019). "We initially suggested that TRPA1, because of it known involvement in some forms of itching, might regular itch in human psoriasis." (PMID 31111624, 2019). "Both TRPA1 antagonists (HC030031 and A967079) significantly inhibited spontaneous behaviors when administered immediately (within 30 min) before assessment, suggesting an important role for TRPA1 in mediating cutaneous discomfort in the Aldara model of psoriasis." (PMID 30204499, 2019). "The suppression of substance P following TRPA1 activation may thus represent another mechanism through which this channel modulates inflammatory responses, with potential implications for the treatment of chronic inflammatory conditions such as psoriasis." (PMID 41597266, 2026). "Lastly, we investigated whether TRPA1, established as a potential trigger for neuropeptide release in tissues that include mouse skin, was involved in mediating the spontaneous behaviors in this psoriasis model." (PMID 30204499, 2019). "Although there are still few studies on the role of TRPs in the therapies currently used for psoriasis, there is evidence of the activation of TRPV1 and the TRPA1 subtypes in the adverse effects of topical pharmacotherapy and phototherapy." (PMID 41689746, 2026). "Interestingly, the TRPA1-deficient mice showed a significant reduction in IMQ-induced psoriatic symptoms, including skin barrier defects and the production of inflammatory mediators, suggesting that TRPA1 plays a crucial role in mediating the pathologic inflammation seen in IMQ-induced psoriasis." (PMID 38474002, 2024). "Conversely, another study reported that TRPA1 genetic deletion sustained the dermal inflammation and the Th17-related cytokines expression in a severe model of IMQ-induced psoriasis, which also induced a systemic inflammatory reaction in mice." (PMID 33802836, 2021). "Therefore, we suggest that TRPA1 may indeed play a positive role in psoriasis." (PMID 31111624, 2019). "Thus, we suggest that TRPA1 supports the production of MCP-1 in keratinocytes in inflammatory conditions, potentially linking TRPA1 to the pathogenesis of psoriasis and other inflammatory conditions of the skin." (PMID 33805042, 2021). "We have recently shown that TRPA1 acts in a protective manner in the murine Aldara model of psoriasis using TRPA1-deleted mice or when a TRPA1 antagonist was administered repeatedly; we did not, however, study the effect of sensory nerve deletion or blockade." (PMID 30204499, 2019). "The present findings build on previous findings to potentially suggest involvement of TRPA1 at multiple sites (such as neuronal and nonneuronal) in this model of psoriasis." (PMID 30204499, 2019). "We found TRPA1 mRNA levels increased 19‐fold in psoriatic skin lesions compared with skin from individuals without psoriasis." (PMID 31111624, 2019). "Interestingly, the TRPA1 channel appears to have dual functions—both positive and negative—in relation to psoriasis pathogenesis, depending on the cell type expressing it." (PMID 38474002, 2024).
atherosclerosis (16 papers, 2017 to 2025). A disease characterized by the build-up of fatty material and calcium deposition in the arterial wall resulting in partial or complete occlusion of the arterial lumen. "In the earlier atherosclerosis mouse model study, macrophages from TRPA1-deficient mice were also shown to have downregulated expression of M2 markers." (PMID 36698198, 2023). "The current study confirmed that TRPA1 is associated with atherosclerosis, and it plays a key role in the macrophage cholesterol outflow and inflammation." (PMID 32903613, 2020). "Atherosclerosis causes chronic inflammation, and the activation of TRPA1 suppresses this inflammation." (PMID 32903613, 2020). "The discrepancy surrounding the protective effect of TRPA1 in atherosclerosis might be caused by the use of different macrophage sources (BMDMs vs. THP-1 derived macrophages) and the different stimuli (Ox-LDL vs. LPC)." (PMID 34768891, 2021). "This problem could, in this specific case at least, be circumvented by excluding patients at risk for atherosclerosis and kidney injury from receiving TRPA1 inhibitors." (PMID 34768891, 2021). "Moreover, TRPA1 may be implicated in cholesterol metabolism and inflammatory disorders, thereby contributing to the development of atherosclerosis." (PMID 38255767, 2024). "The activation of TRPA1 has a protective role against the development of atherosclerosis, and this activation itself produces peripheral vasodilation and induces a biphasic blood pressure response." (PMID 39856994, 2025). "TRPA1 regulates macrophages phenotype plasticity, deletion of TRPA1 increases atherosclerosis plaques." (PMID 37588590, 2023). "Up-regulation of TRPA1 in atherosclerotic plaques can regulate the development of macrophages to the M1 inflammatory phenotype, thereby promoting the progression of atherosclerosis." (PMID 37404813, 2023). "TRPA1 can regulate the development of macrophages to M1 inflammatory phenotype, thereby promoting the progression of atherosclerosis." (PMID 37404813, 2023). "On the other hand, treatment with TRPA1 agonists alleviates the development of atherosclerosis in Apoe-/- mice, indicating that TRPA1 protects against atherosclerosis." (PMID 37588590, 2023). "In recent years, several studies have explored the potential role of TRPA1 channels in atherosclerosis." (PMID 37588590, 2023). "In this context, the dual roles of TRPs such as that of TRPA1 in atherosclerosis must be considered." (PMID 35455971, 2022). "Oxidized low-density lipoprotein (ox-LDL), crucial in the atherosclerosis pathogenesis and the formation of macrophage foam cells, directly activated TRPA1 in transfected HEK293 cells, an effect abrogated in the presence of HC030031." (PMID 34768891, 2021). "Although TRPA1 has a protective function in atherosclerosis and kidney injury, its implication in cardiac hypertrophy seems different." (PMID 34768891, 2021). "Because macrophages play key roles in atherosclerosis onset and progression, it was investigated if TRPA1 was important in the regulation of macrophage activation and polarization." (PMID 34768891, 2021). "In apolipoprotein E (Apoe)-KO mice, a mouse model of atherosclerosis, TRPA1 channel activation with AITC was found to suppress atherosclerotic progression." (PMID 34064835, 2021). "TRPA1, when upregulated in atherosclerosis plaque, regulates the macrophages towards an inflammatory phenotype and alleviates atherosclerosis." (PMID 33810314, 2021). "In sharp contrast with these two studies, TRPA1 seems to exert pro-inflammatory effects in a macrophage cell line in the context of atherosclerosis." (PMID 34768891, 2021). "The chronic administration of the TRPA1 antagonist or genetic ablation increased atherosclerosis, and the chronic administration of the TPRA1 agonist decreased the lesion." (PMID 33810314, 2021). "The activation of TRPA1 channel has a protective effect on the development of atherosclerosis; its channel blockade is beneficial for arrhythmia progression." (PMID 32903613, 2020).
atherosclerosis (continued). "TRPA1, which is upregulated in atherosclerotic plaques, can regulate the inflammatory phenotype of macrophages, thereby regulating the progress of atherosclerosis." (PMID 32903613, 2020). "TRPA1 plays an important role in regulating glycolipid metabolism, which has important significance for the treatment of atherosclerosis." (PMID 32903613, 2020). "TRPA1 agonist allyl isothiocyanate was protective against atherosclerosis and ameliorated MIP-2 release." (PMID 31551776, 2019). "The role of TRPA1 in macrophages was recently investigated in the context of the pathogenesis of atherosclerosis." (PMID 29467763, 2018). "Treatment with the monoclonal antibody E06 or with apolipoprotein A-I mimetic peptide D-4F, capturing OxPAPC in atherosclerosis, prevented inflammatory hyperalgesia, and in vitro TRPA1 activation." (PMID 28710476, 2017). "The suppression of TRPA1 may regulate the differentiation of macrophages towards the M1 inflammatory phenotype and consequently impede the progression of atherosclerosis." (PMID 38255767, 2024). "The hypothesis was inspired by animal studies where genetic ablation of TRPA1 was shown to exacerbate M1-driven diseases atherosclerosis and renal ischemia-reperfusion injury." (PMID 36698198, 2023). "Activation of TRPA1 by cinnamaldehyde decreased atherosclerosis progression." (PMID 37326902, 2023). "TRPA1 may be an important regulator in the pathogenesis of the atherosclerosis and cholesterol metabolism of macrophage foam cells." (PMID 33810314, 2021). "Thus, future studies will be necessary to elucidate the role of TRPA1 channel signaling in macrophage recruitment and polarization under conditions of atherosclerosis." (PMID 34064835, 2021). "Furthermore, the review summarizes the potential role of TRPA1 in regulating the pathophysiology of the cardiovascular system, including vascular physiology, atherosclerosis, myocardial fibrosis, heart failure, and arrhythmia." (PMID 32903613, 2020). "The activation of TRPA1 by cinnamaldehyde significantly slows the progression of atherosclerosis." (PMID 32903613, 2020). "Moreover, inhibition of TRPA1 activity exacerbated atherosclerosis and abated cholesterol efflux by suppressing oxLDL-induced cholesterol efflux but did not alter oxLDL internalization." (PMID 31680989, 2019). "In a mouse high-fat diet-induced atherosclerosis model, TRPA1 was localized mainly in macrophages; TRPA1 channel activation with AITC suppressed the progression of atherosclerosis in apolipoprotein E (apoE)−/− mice, while the protective effect was lost in apoE−/−TRPA1−/− mice." (PMID 31680989, 2019). "In this review, we summarize the potential involvement of the TRPA1 channel in modulating pathophysiologic conditions, including atherosclerosis, heart failure, myocardial ischemia–reperfusion injury (IRI), myocardial fibrosis, arrhythmia, vasodilation, and hypertension." (PMID 31680989, 2019). "Thus, activation of the macrophage TRPA1 channel suppressed atherosclerosis by inhibiting cholesterol efflux and the inflammatory response." (PMID 31680989, 2019). "Recent studies have suggested that the TRPA1 channel plays an essential role in the development and progression of several cardiovascular conditions, such as atherosclerosis, heart failure, myocardial ischemia–reperfusion injury, myocardial fibrosis, arrhythmia, vasodilation, and hypertension." (PMID 31680989, 2019). "Activation of the TRPA1 channel has a protective effect against the development of atherosclerosis." (PMID 31680989, 2019). "However, the link between TRPA1, macrophages, and atherosclerosis remains poorly understood." (PMID 34064835, 2021). "Therefore, TRPA1 plays a crucial role in the mechanism of atherosclerosis formation and it could be a therapeutic target for atherosclerosis and other metabolic diseases." (PMID 32903613, 2020).
atherosclerosis (continued). "It was shown that mice with a double knockout in the TRPA1 and apolipoprotein E (APOE) genes showed an increase in atherosclerosis plaques compared to mice with single knockout in the APOE gene after a high-fat diet treatment." (PMID 37326902, 2023). "The activation of TRPA1 has a positive effect on atherosclerosis, but it has a negative effect on other cardiovascular diseases such as myocardial fibrosis and heart failure." (PMID 32903613, 2020). "The study also revealed that genetic deletion of TRPA1 exacerbated the atherosclerotic lesion in apoE-/- mice, whereas treatment with AITC reduced the atherosclerotic lesion in apoE-/- mice but not in apoE-/-TRPA1-/- mice, suggesting its involvement in atherosclerosis development." (PMID 34912298, 2021).
breast carcinoma (16 papers, 2020 to 2025). "Using The Cancer Genome Atlas Analysis (TCGA) and immunocytochemistry analysis evidenced that TRPA1 was overexpressed in breast cancer." (PMID 40813985, 2025). "The heatmap of the Pearson correlation returned by TIMER.2 shows significant positive correlations with TNF in colon, rectal and breast cancer and glioblastoma, which implies a high stimulation of TRPA1 in inflammatory conditions." (PMID 39770499, 2024). "Experiments using mice with metastatic melanoma and breast cancer have shown that TRPA1 activation induces voluntary pain behavior." (PMID 39273183, 2024). "The inhibition of TRPA1 channel activity by pharmacological means, or by gene silencing, increased cancer sensitivity to carboplatin in in vitro models of lung and breast cancer." (PMID 39594815, 2024). "In contrast, a more recent work proposed a pore-dependent function for TRPA1 in lung and breast cancer pro-survival signaling, which seems to exclude FGFR2 involvement." (PMID 38339360, 2024). "TRPA1 activation in glioma and breast cancer cells induces mitochondrial damage and apoptosis via cytochrome-c, the activation of caspase 3 and 9, and the release of apoptosis-inducing factors and endonuclease G." (PMID 38612571, 2024). "Takahashi and coworkers showed that the removal of extracellular Ca2+ abolished H2O2-evoked, TRPA1-mediated intracellular Ca2+ oscillations in lung and breast cancer cells." (PMID 37174661, 2023). "Opposite results were obtained from breast cancer cells, where inhibition of TRPA1 reduced tumor growth." (PMID 37507867, 2023). "The waveform of this Ca2+ response is quite different from the repetitive oscillations in [Ca2+]i evoked by TRPA1 activation in lung and breast cancer cells." (PMID 37393347, 2023). "Takahashi and coworkers demonstrated that TRPA1 triggers intracellular Ca2+ oscillations to promote ROS resistance in lung and breast cancers." (PMID 37174661, 2023). "In fact, it was revealed that the upregulated expression of TRPA1 observed in breast cancer cells enhances resistance to ROS by triggering Ca2+-dependent signaling pathways that inhibit apoptosis." (PMID 37755210, 2023). "The oxidative stress sensor, transient receptor potential ankyrin 1 (TRPA1), activated by ROS, appears to contribute to lung and breast cancer progression." (PMID 34831352, 2021). "TRPA1 has been shown to be most highly upregulated among all of the TRPs in invasive ductal breast carcinoma, indicating TRPA1 promotes breast cancer progression." (PMID 32211326, 2020). "The TCGA project’s analysis, encompassing data from 31 cancer types, shows that TRPA1 is significantly overexpressed in cancers with different origins, such as kidney cancer, breast cancer, cholangiocarcinoma, head and neck squamous cell carcinoma, and lung, prostate and thyroid cancers." (PMID 39770499, 2024). "Thus, inhibiting the excessive opening of TRPA1 disrupts the oxidative stress defense system acquired by breast cancer cells." (PMID 37755210, 2023). "Including TRPCs, TPRVs, TRPMs, TRPA1, TRPPs, and TRPMLs, calcium homeostasis plays an important role in the occurrence, development, and metastasis of breast cancer, which is related to the response to metal ions (GO:0010038, FDR adjust p value = 9.17E-13)." (PMID 34899291, 2021). "Furthermore, TRPA1 is overexpressed in several cancer types, including breast carcinoma." (PMID 38564162, 2024). "Furthermore, studies using genetic and pharmacological approaches to determine the role of TRPA1 in a murine breast carcinoma model have shown that injections of TRPA1 antagonists and antisense oligonucleotides reduce spontaneous pain-related behaviors and mechanical and cold hypersensitivity." (PMID 39273183, 2024).
breast carcinoma (continued). "For instance, selective TRPA1 agonists (e.g., brain tumors) or blockers (e.g., lung and breast cancers) could be administered as adjuvant drugs of ROS-producing therapeutics, such as carboplatin, doxorubicin, and paclitaxel, to increase cancer cell sensitivity to oxidative stress." (PMID 37174661, 2023). "Indeed, TRPA1 accelerates breast cancer development in two routes." (PMID 32211326, 2020). "In breast cancer and colorectal cancer, TRPM2 activates NRF2 signaling to enhance resistance to oxidative stress, while TRPA1 in glioblastoma alters mitochondrial dynamics and triggers apoptosis via increased fission, Ca2+ influx, and ROS production." (PMID 40813985, 2025). "In summary, our work shows the functional interaction between NCS-1 and TRPA1 in MDA-MB-231 cells, a breast cancer cell line, and SH-SY5Y cells, a neuronal model." (PMID 38564162, 2024). "In breast cancer cells, TRPA1 suppressed apoptosis upon stimulation by H2O2, whereas TRPA1 inhibition increased cell apoptosis in response to platinum-based drugs." (PMID 37507867, 2023). "Within this review, we will assess the existing understanding of how five specific TRP channels (TRPA1, TRPC5, TRPV1, TRPV2, and TRPM2) contribute to the resistance of breast cancer to therapeutic interventions." (PMID 37755210, 2023). "All in all, considering the drug resistance by TRPA1 and TRPP2 reported in breast cancers, these two channels probably are essential for tumor development in the late-stage, like bone metastasis." (PMID 32211326, 2020). "Future work will have to examine the possibility that TRPA1 channels on the plasma membrane are juxtaposed to ER-located inositol-1,4,5-trisphosphate receptors in some, e.g., lung and breast cancers, but not all solid malignancies." (PMID 37393347, 2023). "The outcome of TRPA1 stimulation by oxidative stress may vary depending on the tumor type: for instance, TRPA1-mediated Ca2+ entry engages a non-canonical anti-oxidant defense program in lung and breast cancers, while it stimulates mitochondrial dysfunction and apoptosis in glioblastoma multiforme." (PMID 37393347, 2023).